ONECUT1 (one cut homeobox 1)
Description:
Transcriptional activator. Binds the consensus sequence 5'-DHWATTGAYTWWD-3' on a variety of gene promoters such as those of HNF3B and TTR. Important for liver genes transcription.
Synonyms: HNF-6; HNF6; HNF6A
Tractability: No criterion of Open Targets' tractability assessment is met for any kind of drug.
Gene: Protein-coding gene on chromosome 15 (52,755,053 to 52,791,078, reverse strand). Ensembl gene ENSG00000169856.
Subcellular location: Nucleus
Subcellular location (Human Protein Atlas): Nucleoplasm
Pathways (Reactome):
Developmental Biology: Developmental Lineage of Multipotent Pancreatic Progenitor Cells; Developmental Lineage of Pancreatic Acinar Cells; Developmental Lineage of Pancreatic Ductal Cells; Regulation of gene expression in early pancreatic precursor cells; Regulation of gene expression in late stage (branching morphogenesis) pancreatic bud precursor cells
Gene Ontology:
Molecular function: sequence-specific double-stranded DNA binding; DNA-binding transcription activator activity, RNA polymerase II-specific; DNA-binding transcription factor activity, RNA polymerase II-specific; RNA polymerase II cis-regulatory region sequence-specific DNA binding; chromatin binding; DNA binding; DNA-binding transcription factor activity
Biological process: positive regulation of transcription by RNA polymerase II; regulation of DNA-templated transcription; regulation of transcription by RNA polymerase II
Cellular component: nucleoplasm; chromatin; nucleus
Genetic constraint (gnomAD): Loss-of-function variants: 12 observed, 23.63 expected, observed/expected ratio (o/e) 0.51, 90% interval 0.32 to 0.82. The upper end of that interval is the gene's LOEUF score, 0.82, which puts it in group 3 of 6, group 1 being the genes least tolerant of losing a copy. Missense variants: 620 observed, 610.13 expected, observed/expected ratio (o/e) 1.02, 90% interval 0.95 to 1.09. Synonymous variants: 285 observed, 249.09 expected, observed/expected ratio (o/e) 1.14, 90% interval 1.04 to 1.26.
Homologues: Orthologues: chimpanzee ONECUT1 (99% identical), macaque ONECUT1 (99% identical), dog ONECUT1 (99% identical), rat Onecut1 (99% identical), mouse Onecut1 (99% identical), rabbit ONECUT1 (99% identical), guinea pig ONECUT1 (96% identical), tropical clawed frog onecut1 (87% identical), zebrafish onecut1 (83% identical), pig ONECUT1 (80% identical), Drosophila melanogaster onecut (48% identical), Caenorhabditis elegans ceh-48 (40% identical), and 4 more. Paralogues in human: ONECUT2 (68% identical), ONECUT3 (57% identical).
Diseases named in the same sentence as ONECUT1 in open-access papers:
ONECUT1 is named in the same sentence as 45 diseases in open-access papers, as found by Europe PMC text mining. Sharing a sentence is not in itself a finding about the gene and the disease. The quoted sentences say what the papers report.
diabetes (15 papers, 2020 to 2025). "Variants identified in the coding region of ONECUT1 gene in patients with different subtypes of diabetes mellitus." (PMID 37941991, 2023). "Our data from Arab individuals with diabetes support the involvement of ONECUT1 variants, particularly the rs202151356_p.H33Q, in various forms of diabetes, especially MODY, T1D, and T2D." (PMID 37941991, 2023). "The researchers identified 13 ONECUT1 heterozygous variants in patients with different subtypes of diabetes." (PMID 37941991, 2023). "The data from Arab individuals with diabetes further support the recurrent involvement of ONECUT1 variants, particularly the homozygous variants of rs202151356_p.H33Q and rs61735385_p.P94P, in various forms of diabetes." (PMID 37941991, 2023). "One Cut Homeobox 1 (ONECUT1) encodes for a transcription factor enriched in the liver and variants in it are associated with different forms of diabetes that is a known risk factor for severe outcomes in COVID-19." (PMID 36143338, 2022). "ONECUT1: rs202151356_p.H33Q) variant observed in datasets of Arab individuals with diabetes." (PMID 37941991, 2023). "Our study observed two homozygous ONECUT1 variants in Arab patients of diabetes—the deleterious missense rs202151356_p.H33Q was observed in 1 individual of MODY, 1 individual of T1D and two individuals of T2D; and the synonymous rs61735385_p.P94P was observed in two T2D individuals." (PMID 37941991, 2023). "Our study generalizes the association of ONECUT1 with clinical diversity in diabetes." (PMID 37941991, 2023). "Further, to examine the epigenetic involvement of the ONECUT1 variants in diabetes, we used mQTLdb to examine whether the observed ONECUT1 variants are QTLs for methylation sites in and around the gene region." (PMID 37941991, 2023). "Additionally, our findings demonstrate the involvement of the ONECUT1 variants in regulating the transcriptional and epigenetic machinery relating to diabetes." (PMID 37941991, 2023). "Interestingly, ONECUT1, a genetic risk gene for monogenic recessive diabetes, has been shown to directly repress expression of MAFA, the key regulator of insulin expression in β‐cells, suggesting that the regulatory network that underlies insulin control in vivo is maintained on‐chip." (PMID 36285680, 2022). "In 2 subjects, 1 with isolated diabetes, NGS revealed heterozygous variants in 2 recessive genes known to cause syndromic PNDM (RFX6, ONECUT1)." (PMID 38408297, 2024). "Examining diverse populations, such as Arabs known for consanguinity, can generalize the ONECUT1 involvement in diabetes." (PMID 37941991, 2023). "Here we examine the role of ONECUT1 variants in NDM, MODY, and type 2 diabetes in large international cohorts of subjects with monogenic diabetes and >400,000 subjects from UK Biobank." (PMID 37639628, 2023). "In summary, we highlight the significance of ONECUT1 as a recurrent marker for diabetes." (PMID 37941991, 2023). "We examined data from our ongoing methylation study to determine whether differential methylation events occur in response to diabetes in the genome region harbouring the ONECUT1 gene." (PMID 37941991, 2023). "Further, our data from comparing the DNA methylation profiles of MODY-X nonautoimmune diabetes patients and healthy individuals suggested an epigenetic involvement of ONECUT1 gene via differential DNA methylation in patients with MODY-X." (PMID 37941991, 2023). "Interestingly, our study highlights ONECUT1 methylation as a potential marker for MODY-X, representing either a unique subtype of MODY or a form of diabetes that is yet to be classified." (PMID 37941991, 2023).
hepatocellular carcinoma (8 papers, 2010 to 2025). A malignant tumor that arises from hepatocytes. "The gene ONECUT1 is associated with hepatocellular carcinoma." (PMID 36233190, 2022). "Furthermore, ONECUT1 may also play a role in the prevention of hepatocellular carcinoma and pancreatic cancer by acting as a tumor suppressor." (PMID 35582526, 2022). "In contrast to ONECUT1, ONECUT2 expression has been shown to be elevated in multiple different cancers, including prostate cancer, ovarian cancer, gastric cancer, colorectal cancer, hepatocellular carcinoma, lung adenocarcinoma, and neuroendocrine tumors." (PMID 35582526, 2022).
type 2 diabetes (5 papers, 2022 to 2025). "For instance, deletion of a type 2 diabetes-associated enhancer within the ONECUT1 locus reduced the number of one cut homeobox 1 (ONECUT1)- and pancreatic and duodenal homeobox 1 (PDX1)-positive pancreatic progenitors, implicating this element in early beta cell differentiation." (PMID 40768044, 2025). "Recently, biallelic variants in ONECUT1 were reported as a cause of neonatal diabetes mellitus (NDM) in two subjects, and missense monoallelic variants were associated with type 2 diabetes and possibly maturity-onset diabetes of the young (MODY)." (PMID 37639628, 2023). "Our results confirm biallelic ONECUT1 variants as a cause of NDM and highlight monoallelic null variants as a risk factor for type 2 diabetes." (PMID 37639628, 2023).
Hepatic steatosis (3 papers, 2019 to 2025). Steatosis is a term used to denote lipid accumulation within hepatocytes. "Additionally, Onecut1 and Cd74 were down-regulated in telmisartan-treated liver tissues but, in contrast to the present findings, these genes were inhibited during hepatic steatosis induction." (PMID 30850637, 2019).
colorectal cancer (2 papers, 2021 to 2024). A primary or metastatic malignant neoplasm that affects the colon or rectum. "The mechanism may be that ONECUT1 promotes the proliferation and tumor growth of colorectal cancer cells and promotes liver metastasis by endogenic resistance to anoikis." (PMID 39099656, 2024). "ONECUT1 is highly expressed in colorectal cancer and has a poor prognosis." (PMID 39099656, 2024).
liver cancer (2 papers, 2023 to 2025). An epithelial or non-epithelial malignant neoplasm that arises from the liver. "The involvement of ONECUT1 in the regulation of miR-122 underscores its significance in liver cancer and highlights its potential as a therapeutic target for this disease." (PMID 37744879, 2023). "Onecut1 is also involved in liver cancer by regulating miR-122, a tumor suppressor microRNA." (PMID 37744879, 2023).
lung carcinoma (2 papers, 2016 to 2024). "ONECUT1 and ONECUT2 have been reported in tumors: highly active ONECUT1 can suppress the proliferation and metastasis of colorectal and lung cancer cells, whereas ONECUT2 acts as a survival factor and a driver of prostate cancer." (PMID 38386414, 2024).
MODY (2 papers, 2023). "Upon examining the study exome datasets of individuals with MODY, T1D and T2D for variants from ONECUT1, we observed two homozygous variants, namely, the deleterious missense rs202151356_ p.H33Q, and the synonymous rs61735385_p.P94P." (PMID 37941991, 2023). "Thus, the observed ONECUT1 methylation in the MODY patients in this study can help to clarify when suspected MODY individuals are misdiagnosed as T1D patients." (PMID 37941991, 2023). "However, we found no enrichment of missense or null ONECUT1 variants among 484 individuals clinically suspected of MODY, in whom all known genes had been excluded." (PMID 37639628, 2023).
pancreatic cancer (2 papers, 2023). "ONECUT1 expression loss plays a key role in human pancreatic cancer cells." (PMID 36741260, 2023). "In pancreatic cancer, differential hydroxymethylation of genes related to pancreas development or function (GATA4, GATA6, PROX1, ONECUT1, MEIS2), and cancer pathogenesis (YAP1, TEAD1, PROX1, IGF1) have also been shown to reliably identify pancreatic cancer from peripheral blood samples." (PMID 36835649, 2023).
scrub typhus (2 papers, 2021 to 2023). Scrub typhus is a rare dust mite-borne infectious disease caused by the Orientia tsutsugamushi bacterium and characterized clinically by an eruptive fever which is potentially serious. "Rs2059950 of the DTW domain containing 2 (DTWD2) gene and rs74744256 of the one cut homeobox 1 (ONECUT1) and WD repeat domain 72 (WDR72) gene also showed a significant association of scrub typhus with p < 1 × 10−5." (PMID 33807835, 2021).
Abdominal obesity (1 paper, 2022). Excessive fat around the stomach and abdomen. "The most significant association with abdominal obesity was found for the AB-L3:ONECUT1 gene of the peri-menopausal male group (p-value = 8.64 × 10−10)." (PMID 36233190, 2022). "The SNP rs1899752 variant on ONECUT1 was associated with a lower risk of abdominal obesity in young men." (PMID 36233190, 2022).
Alagille syndrome (1 paper, 2021). "The most extreme example of such a process is exemplified in a mouse model of Alagille syndrome, in which hepatoblasts lack notch signaling and the biliary transcription factor Onecut1 (Hnf6), leading to the absence of an intrahepatic biliary tree at birth." (PMID 33974812, 2021).
amelogenesis imperfecta (1 paper, 2022). Amelogenesis imperfecta (AI) represents a group of developmental conditions affecting the structure and clinical appearance of the enamel of all or nearly all the teeth in a more or less equal manner, and which may be associated with morphologic or biochemical changes elsewhere in the body. "SIX1 is a master regulator in multiple tissues and ONECUT1 is a transcription factor of the liver; and are associated with the craniofacial disorders branchiootic syndrome and amelogenesis imperfecta, respectively." (PMID 35711735, 2022).
cervical cancer (1 paper, 2016). A primary or metastatic malignant neoplasm involving the cervix. "Of the 53 differentially methylated candidates that were found in both ADC and SCC, 20 genes were described previously in literature as being more frequently methylated in cancer, and 6 genes in (squamous-cell) cervical cancer (SOX1, SOX14, ONECUT1 and WT1) or high-grade CIN (GFRA1, SOX1 and TBX20)." (PMID 27738327, 2016).
epilepsy (1 paper, 2024). A brain disorder characterized by episodes of abnormally increased neuronal discharge resulting in transient episodes of sensory or motor neurological dysfunction, or psychic dysfunction. "A notable example includes the rs20756613 SNP within the ONECUT1 host gene in the white non-Hispanic group and its association with epilepsy and various other clinical features, such as intellectual disability (ID) and language delay." (PMID 38760502, 2024).
steatosis (1 paper, 2024). Increased lipid within the cytoplasm of cells. "The sub-network of ONECUT1 consists of 44 differentially expressed genes, many of which are involved in fatty acid metabolism and are highly correlated with the progression of steatosis." (PMID 39350187, 2024).
tumor (18 papers, 2008 to 2025). "A loss of ONECUT1 expression in PDAC cells implied its tumor suppressor function in this malignant tumor." (PMID 33178697, 2020). "Given that activation of these pathways were involved in tumour development, these observations indicate that down‐regulation of ONECUT1 and PHYHIPL can induce activation of these key pathways to promote iCCA progression." (PMID 34013637, 2021). "This activity highlights the potential tumor suppressive role of ONECUT1." (PMID 37744879, 2023). "These hepatoprotective mediators (Egfr, Lifr, Onecut1) are also highly oncogenic and tight control of their expression could therefore contribute to the delayed onset of neoplasia in Ames dwarf mice." (PMID 30462643, 2018). "Studies in mouse indicate ONECUT1 has tumor suppressor activity." (PMID 26039411, 2015). "Finally, the lipid metabolism gene sets show strong association of HNF6 (Onecut1) and PPAR-gamma with the tumor state." (PMID 21464922, 2011). "Key hub genes SLC2A1, CDH3 and EFHD2 showed increased expression across the tumour stage and were correlated with poor survival, whereas decrease of FAM171A1, ONECUT1 and PHYHIPL was correlated with better survival." (PMID 34013637, 2021). "Consistent with the trend of overall expression of hub genes, expression of FAM171A1, ONECUT1 and PHYHIPL decreased across the tumour stage." (PMID 34013637, 2021). "As a result, we identified CDH3, EFHD2 as tumour‐promoting genes, and ONECUT1, PHYHIPL as tumour suppressing genes." (PMID 34013637, 2021). "In contrast genes involved in development and differentiation (Arid5b, Inmt, Grem2, Gdap10), cell metabolism (Alas1, Gsta1, Thrsp, Fdft1, Elovl6), tumor growth (SerpinA4, Cish, Rpl36), and cell cycle control (PLK3, Myc, HNF6/Onecut1) were downregulated." (PMID 33004985, 2020). "Moreover, our findings revealed key pathways mediated by suppression of ONECUT1 and PHYHIPL for the tumour progression." (PMID 34013637, 2021). "ONECUT1, ADAMTS, IFNAR2, MSR1, and SORL1 affect migration or metastasis, a process that involves attachment of tumor cells to the basement membrane, degradation of local connective tissue, and penetration and migration of tumor cells through stroma." (PMID 23151184, 2012). "For example, the downregulation of Onecut1 and upregulation of Ifitm3 might inhibit cell proliferation, whereas the downregulation of GADD45G might enhance tumor cell growth." (PMID 18307821, 2008).
cancer (16 papers, 2010 to 2025). A tumor composed of atypical neoplastic, often pleomorphic cells that invade other tissues. "Among the genes with increased 5hmC density in PDAC were those related to pancreas development (GATA429, GATA629, PROX130, ONECUT131, and MEIS232) and/or implicated in cancer (YAP133, TEAD133, PROX134, ONECUT2, ONECUT1, and IGF1)." (PMID 33077732, 2020). "Several cancer-promoting genes were uperegulated (Ctgf, H19, Mmp12, Mybl1, Vnn1) while cancer inhibiting genes (Cish, Dkk4, Onecut1, Scara5, Socs3, Wif1) were suppressed." (PMID 26200659, 2015). "HNF4A is expressed widely in cancers of the gastrointestinal tract, biliary tree, and pancreas as opposed to HNF6, encoded by the ONECUT1 gene, whose expression is restricted to liver and small bile duct carcinomas." (PMID 41425714, 2025). "The ONECUT1 (one cut homeobox 1) gene is a DNA consensus sequence-binding transcription factor activator of RNA polymerase II-specific DNA-binding transcription, influencing glucose metabolism and cancer cell cycle regulation." (PMID 39589950, 2024). "On the other hand, several HBV inhibitors, for example, ONECUT1, RFX1, and SIRT1 appeared to be up-regulated in less differentiated cancer cells." (PMID 34290079, 2021). "Differential hydroxymethylation is found in thousands of genes, most significantly in genes related to pancreas development or function (GATA4, GATA6, PROX1, ONECUT1, MEIS2), and cancer pathogenesis (YAP1, TEAD1, PROX1, IGF1)." (PMID 33077732, 2020).
metabolism disorders (1 paper, 2021). "Based on the pseudo-temporal continuum profile, we identified the TF (ALX4, HINFP, CEBPA, CEBPB, DMBX1, MLXIPL, ONECUT1, and RBPJL) and depicted the regulated kernel genes co-networks, which were subjected to the metabolism disorders." (PMID 33462196, 2021).
ONECUT1 also shares sentences with these, for which no sentence is quoted: hepatic (2 papers); Hepatic fibrosis (2); autism (1); biliary atresia (1); brain cancer (1); branchiootic syndrome (1); cholestasis (1); colon carcinoma (1); colorectal (1); COVID-19 (1); Glucose intolerance (1); hepatoblastoma (1); insulinoma (1); Intellectual disability (1); language delay (1); liver diseases (1); lung adenocarcinoma (1); metastatic tumor (1); neonatal diabetes mellitus (1); pancreatic ductal adenocarcinoma (1); permanent neonatal diabetes mellitus (1); prostate carcinoma (1); protein c deficiency (1); schizophrenia (1); Sepsis (1); Venous thrombosis (1).